IGF1R (insulin like growth factor 1 receptor)
Diseases named in the same sentence as IGF1R in open-access papers (continued):
Sharing a sentence is not in itself a finding about the gene and the disease.
ovarian carcinoma (continued). "In ovarian cancer, miR-217 acted as a tumor suppressor role by targeting IGF1R." (PMID 34302635, 2021). "provide evidence that IGF-1R axis inhibition could be a therapeutic strategy for ovarian cancer by restoring dendritic cell (DC)-mediated antitumor immunity." (PMID 34804946, 2021). "In ovarian cancer cells, IGF1-R undergoes upregulation as a consequence of miR-1294 downregulation." (PMID 32503307, 2020). "Transwell migration and invasion assays further revealed that IGF1R positively regulates ovarian cancer cell migration and invasion of as well, meaning that IGF1R positively regulates the oncogenesis of ovarian cancer." (PMID 32284739, 2020). "In order to know whether miR-194-5p regulates the tumorigenesis of ovarian cancer through IGF1R, we overexpressed or knocked down its expression by an IGF1R overexpression vector or a specific shRNA." (PMID 32284739, 2020). "It is worth mentioning that IGF1-R-mediated EMT may be involved in resistance of ovarian cancer cells in response to CP therapy." (PMID 32503307, 2020). "In summary, our results suggest that the interplay between IGF-1R and ErbB3 may serve as a regulator of tumor growth and resistance to chemotherapies in ovarian cancer." (PMID 31728045, 2019). "There are currently very few studies of IGF-1R in ovarian cancer patients." (PMID 29731973, 2018). "In addition to monoclonal antibodies, small molecule IGF1R inhibitors such as NVP-AEW541 had anti-proliferative effects on ovarian cancer cells." (PMID 29922232, 2018). "Considering these results, it was then relevant to question whether blocking IGF1R in DCs would have a significant effect on ovarian carcinoma cells." (PMID 29922232, 2018). "In addition, a previous study showed that IGF1R-targeted therapy has significant anti-neoplastic activity in ovarian cancer cells." (PMID 29922232, 2018). "Hence, we presumed that TMED2 regulation of epithelial ovarian cancer proliferation, migration and invasion involves IGF1R/IGF2/PI3K/AKT pathway." (PMID 29212217, 2017). "IGF1R expression level is raised in non-BRCA1-mutated ovarian cancer cells compared with normal tissue and additionally IGF1R levels are significantly increased in BRCA1-inactivation ovarian cancer." (PMID 27405474, 2016). "This suggests that the IGF-1R may be a potential co-targeting option for other cancers such as ovarian cancer that are currently treated with cisplatin." (PMID 27472395, 2016). "Previously we showed that upregulated IGF-1R expression is essential to initiate platinum-taxol resistance at early stage which declines with elevated levels of activated AKT at late resistant stage in ovarian cancer cells." (PMID 27819360, 2016). "Thus our data suggests that dynamic changes in chemoresistance development in ovarian cancer cells influence functionality of CSC pool which is tightly regulated by IGF-1R-AKT signalling cascade." (PMID 27819360, 2016). "Moreover, hyper-activation of IGF-1R has been found to be essential for cisplatin resistance in ovarian cancer." (PMID 27472395, 2016). "The observations of the current study indicate that BRCA1 may be a potential trigger that is involved in the transcriptional regulation of IGF1R in the development of ovarian cancer." (PMID 24765210, 2014). "Notably, the knockdown of BRCA1 was observed to be an effective method of inducing an increase of IGF1R levels in SKOV3 and non-BRCA1-mutated ovarian cancer cells." (PMID 24765210, 2014). "Furthermore, dysregulation of IGF1R is found in many cancers including ovarian cancer, where overexpression of IGF1R correlates with poor prognosis." (PMID 25115504, 2014). "In this paper, we will focus on the role of IGF-1R in ovarian cancer tumorigenesis and treatment." (PMID 24103397, 2013). "We examined the expression of IGF-1R in surgical specimens of epithelial ovarian cancer by IHC." (PMID 24103397, 2013).
ovarian carcinoma (continued). "Notably, inhibition of IGF-1R by AS dramatically increased the sensitivity of ovarian cancer cells to the chemotherapeutic agent cisplatin compared with either agent alone." (PMID 24103397, 2013). "Immunofluorescence double-labeling of RMG-I-H cell and ovarian cancer tissue detected Lewis(y) predominantly localized to the cell membrane (green fluorescence) and IGF-1R localizing mostly to the cell membrane but occasionally to the cytoplasm (red fluorescence)." (PMID 22072919, 2011). "The average optical density of IGF-1R in low-differentiated ovarian cancer samples was 0.455 ± 0.049, which was significantly higher than the optical densities measured in moderate- (0.413 ± 0.038) (P < 0.05) and high-differentiation samples (0.412 ± 0.052) (P < 0.05)." (PMID 22072919, 2011). "Lewis(y) and IGF-1R are relevant to staging and differentiation of ovarian cancer, suggesting that these two molecules mediate a boosting function for the development of ovarian cancers." (PMID 22072919, 2011). "Numerous studies have confirmed that IGF-1R plays an important role in ovarian cancer progression." (PMID 22072919, 2011). "Furthermore, we examined whether ME could regulate the HSP90AB1/IGF1R interaction so as to overcome cisplatin resistance and induce apoptosis in ovarian cancer cells." (PMID 37180757, 2023). "However, it was unknown whether SNHG20/miR-217 regulated the progression of ovarian cancer by regulating IGF1R gene or other target genes." (PMID 34302635, 2021). "However, to our knowledge, there is currently no comprehensive study on the relative expression, cellular location and prognostic significance of all members of the HER family, c-MET, IGF-1R, and the putative ovarian cancer stem cell biomarker in patients with ovarian cancer." (PMID 29731973, 2018). "Therefore, the induced expression of IGF1R may be the result of a complex interaction of specific factors in ovarian cancer cells." (PMID 24765210, 2014). "Therefore, it may be predicted that BRCA1 inactivation-related high levels of IGF1R may be involved in promoting ovarian cancer progression." (PMID 24765210, 2014). "However, the crosstalk between the BRCA1 and IGF1R signaling pathways in ovarian cancer remains largely unknown." (PMID 24765210, 2014). "Therefore, IGF-1R is a potential molecular target in ovarian cancer." (PMID 24103397, 2013). "Using pooled human and murine ovarian cancer sera, we observed that pharmacological inhibition of c-MET (AMG337) and IGF-1R (PPP) significantly attenuated AIG colony formation." (PMID 40804939, 2025). "RNA sequencing combined with bioinformatics analysis showed that HSP90AB1 and IGF1R, two known drug-resistance genes, are overexpressed in A2780/CDDP cells, and we found that HSP90AB1 promotes IGF1R expression in ovarian cancer cells." (PMID 37180757, 2023). "In support, ER‐independent IGF‐1R, TGF‐β, JAK/STAT3, MAPK/ERK and PI3K/Akt were also previously reported to mediate BPA actions in ovarian cancer cells." (PMID 37610061, 2023). "Our study found that ME treatment effectively reversed HSP90AB1 overexpression, downregulated the expression of cancer-related factors IGF1R and MYC, and exerted anti-tumorigenic effects in ovarian cancer." (PMID 36362498, 2022). "In another study, decreased PTP1B expression was observed in various ovarian cancer cell lines compared to normal epithelial cells, and stable restoration of PTP1B was shown to antagonize IGF1R signalling pathway in these cancer cells." (PMID 35296731, 2022). "Activation of the IGF1R/STAT3 signaling axis contributes to enhanced invasion and migration in ovarian cancer." (PMID 34185427, 2021). "In ovarian cancer, knocking out miR-194-5p promotes the expression of IGF1R and PPFIBP1, which in turn promotes the proliferation, migration, and invasion of ovarian cancer cells." (PMID 34052838, 2021).
ovarian carcinoma (continued). "Taken together, our results suggested a NF-κB modulated miR-194-5p/IGF1R/ PPFIBP axis that is crucial for the tumorigenesis of ovarian cancer, which provides a new insight into the development of ovarian cancer." (PMID 32284739, 2020). "In this study, we found that both IGF1R and PPFIBP1 expression can be inhibited by miR-194-5p in ovarian cancer, and downregulation of miR-194-5p promotes the oncogenesis of ovarian cancer by increased expression of both IGF1R and PPFIBP1." (PMID 32284739, 2020). "We further found that IGF1R and PPFIBP are targets of miR-194-5p, and downregulation of miR-194-5p expression increases IGF1R and PPFIBP expression, resulting in increased proliferation, invasion and migration of ovarian cancer cells." (PMID 32284739, 2020). "After establishing that most investigated tumor subtypes exhibited IGF1R/PCNA colocalization, we investigated how the interaction was affected by irradiation in ovarian cancer tissue ex vivo." (PMID 32701997, 2020). "While an earlier study reported that of 80 ovarian cancer cases (FIGO I–IV), only 9 (11%) of patients were IGF-1R positive, more recent studies have shown that IGF-1R expression was high (>50%) particularly in high-grade ovarian cancer cases." (PMID 29731973, 2018). "A recent study identified high levels of PAPP-A in the ascites of ovarian cancer patients and more cleaved than intact IGFBP4, indicating that PAPP-A increased IGF activity and therefore stimulated tumour growth via IGF1-R stimulation." (PMID 30348128, 2018). "Metformin can improve the sensitivity of ovarian cancer CP70 cells to cisplatin in a concentration-dependent manner by activating the AKT signaling pathway, inhibiting the IGF1R signaling pathway, and reducing MRP2 expression." (PMID 29241458, 2017). "The model was calibrated and validated using an ovarian cancer cell line, OVCAR5, and then analyzed to determine the relative impact of IGF2R and IGFBPs on IGF2-mediated IGF1R activation." (PMID 26861122, 2016). "Our report thus specifies IGF-1R-AKT signaling as a prime determinant of cancer stem cell functionality and chemoresistance and a potential therapeutic target axis in ovarian carcinoma." (PMID 27819360, 2016). "Intriguingly AKT inhibition resulted in marked increase in IGF-1R levels, suggesting of a possible feedback loop in the IGF-1R-AKT axis during development of chemoresistance in ovarian cancer cells." (PMID 27819360, 2016). "Given that PRKCZ expression correlates with the expression of both IGF1R and ITGB3, we further examined if alteration of these genes can affect the migration phenotype of ovarian cancer cells that over-express PRKCZ." (PMID 25874946, 2015). "Our previous study reported the trastuzumab-resistant ovarian cancer cells, SKOV3-T, with lower HER2 and higher IGF-1R and HER3 expression level than parent SKOV3 cells." (PMID 25424625, 2014). "In our previous work, an acquired trastuzumab-resistant cell model of human ovarian cancer, SKOV3-T, was established, and IGF-1R molecule was found by microarray analysis and preliminarily testified to be pivotal in cell proliferation." (PMID 25424625, 2014). "Previously, we established a trastuzumab-resistant ovarian cancer cell line, named as SKOV3-T, with lower HER2 and induced higher IGF-1R expression level to keep cell survival." (PMID 25424625, 2014). "Combined, these studies suggest that changes that increase the potential for IGF1-IGF1R interaction (i.e., increased IGF1/IGF1R, decreased IGFBPs) promote ovarian cancer and that the IGF network is a promising therapeutic target." (PMID 25115504, 2014). "We report that the ovarian cancer cells from patients with advanced EOC produce endogenous IGF-1, express IGF-1R and grow autonomously in serum-free media (SFM)." (PMID 24103397, 2013).
ovarian carcinoma (continued). "In summary, transfection of the ovarian cancer cell line RMG-I with α1,2-FT leads to increased Lewis(y) content on surface-expressed IGF-1R proteins, suggesting that the elevated expression level of Lewis(y) and IGF-1R are associated with ovarian cancer." (PMID 22072919, 2011). "Three PTKs, janus kinase 1, insulin-like growth factor 1 receptor, and discoidin domain receptor 1 (DDR1), were identified and only DDR1 was overexpressed in all ovarian cancer tissues examined for the validation by quantitative real-time PCR." (PMID 21541037, 2011). "Downregulation of PTK6 also prevented IGF-1 stimulated anoikis resistance of DOV-13 ovarian cancer cells, which co-express PTK6 and IGF-1R." (PMID 20668531, 2010). "In ovarian cancer cells, BPA enhanced the crosstalk between ERα and IGF1R signaling pathways." (PMID 36729355, 2023). "An example is B003-2A, a recently developed IGF-1R anti-idiotypic antibody antagonist, which abrogated the IGF-1R-mediated proliferation of ovarian cancer cells in vivo and in vitro and overcame resistance to cisplatin in ovarian cancer cell lines." (PMID 36017326, 2022). "Our data suggest that ME could suppress oncogenes IGF1R and MYC by inhibiting HSP90AB1 expression, further promoting apoptosis of ovarian cancer cells." (PMID 36362498, 2022). "Furthermore, the IGF1 receptor (IGF1R), which mediates the biological actions of IGF1, is overexpressed in most tumors and cancer cell lines, including ovarian cancers." (PMID 34220714, 2021). "Our analysis of correlation between RTK expression and chemotherapy sensitivity in multiple ovarian cancer cell lines suggested a correlation for IGF-1R and cMET expression, but not ErbB3." (PMID 31728045, 2019). "Despite the promising preclinical reports, clinical trials did not provide meaningful benefit for ovarian cancer patients treated with IGF-1R inhibitors." (PMID 31728045, 2019). "The aim of the present study was to determine the relative expression, cellular location, and prognostic significance of HER-family members, the EGFR mutant (EGFRvIII) c-MET, IGF-1R and the cancer stem cell biomarker CD44 in 60 patients with FIGO stage III and IV ovarian cancer." (PMID 29731973, 2018). "Hence, instead of directly targeting IGF-1/IGF-1R, which has adverse effect on glucose hemostasis, activating PON2 would be a fruitful alternative strategy for treating ovarian cancer." (PMID 29531225, 2018). "This is the first report on an intricate and interdependent relation between IGF-1R and AKT with functional heterogeneity of ovarian cancer stem cells which might emerge as a therapeutic target for the resistant disease." (PMID 27819360, 2016). "Monensin was shown to target multiple cancer-related signaling pathways including Elk1/SRF, AP1, NFκB and STAT, and suppress the expression of EGFR, but not IGF-1R, in ovarian cancer cells." (PMID 26639992, 2015). "However, further clarification of the complex interactions between the BRCA1 and IGF1R signaling pathways, at the transcriptional, post-transcriptional and epigenetic levels, may improve the current understanding of the basic molecular mechanism of ovarian cancer." (PMID 24765210, 2014). "In summary, IGF2 knockdown, but not selective IGF1R inhibition, effectively reverses drug resistance in a Taxol-resistant human ovarian carcinoma xenograft model." (PMID 24932685, 2014). "qPCR and immunohistochemical analysis showed that the levels of IGF1R mRNA and protein were increased in non-mutated and BRCA1-mutated ovarian cancer tissue compared with their adjacent normal tissue." (PMID 24765210, 2014).
ovarian carcinoma (continued). "The DDR1 gene was overexpressed in all eight individuals, whereas the expression levels of JAK1 and IGF1-R were not increased in half of the ovarian cancer tissue samples." (PMID 21541037, 2011). "In high-, moderate-, and low-differentiation ovarian cancer tissues, the positivity rates of IGF-1R were 76.19%, 85.71%, and 94.44%, respectively, and no statistical significance was detected among the three group comparisons (P > 0.05)." (PMID 22072919, 2011). "As with Lewis(y), the expression intensity of IGF-1R was not correlated with the histological type of ovarian cancer or with lymph node metastasis (P > 0.05)." (PMID 22072919, 2011). "Fortunately, in our model system of Cisplatin resistant ovarian cancer, we did not detect coactivation of other RTKs besides IGF-1R." (PMID 21967738, 2011). "We sought to determine whether PTK6 plays a critical role in modulating anchorage-independent survival of breast and ovarian cancer cells in which PTK6 is highly expressed, particularly those which co-express IGF-1R." (PMID 20668531, 2010). "Similarly experimentally induced paclitaxel resistance was associated with elevated IGF2 mRNA, while knockdown of IGF2, but not insulin-like growth factor 1 receptor (IGF1-R), restored sensitivity to paclitaxel in ovarian cancer cell lines." (PMID 41007637, 2025). "Interestingly, our recent study also revealed that monensin effectively inhibited EGFR and tumor grow in human ovarian cancer, however no inhibition to IGF1R was observed." (PMID 36896461, 2023). "Interestingly, while the anti-IGF-1R Clone 24–31 mAb stained the IGF-1R positive control placenta, none of the 60 ovarian cancer specimens were IGF-1R positive." (PMID 29731973, 2018). "However, adiponectin reduced the expression of ERα and IGF1R, but not that of ERβ, in epithelial ovarian cancer cells." (PMID 29603059, 2018). "Whether and how IGF-1R signaling influences the stemness phenotype in chemoresistant ovarian cancer cells is never investigated." (PMID 27819360, 2016). "Our data further illustrate that up-regulation of PRKCZ leads to expression alterations of IGF1R and ITGB3 in SKOV3 and OVCAR3 cell lines, suggesting that PRKCZ may participate in ovarian cancer progression by modulating the expression of other important signalling molecules." (PMID 25874946, 2015). "Therefore, understanding the complex interrelationship between IGF1R and BRCA1 may improve the current understanding of the basic molecular mechanism of ovarian cancer." (PMID 24765210, 2014). "Although therapeutic agents targeting the IGF1-R and small molecule tyrosine kinase inhibitors within the IGF signaling pathway have been investigated in the context of ovarian cancer, IGF-I/II monoclonal antibodies have not yet been explored." (PMID 41007637, 2025). "While ovarian surface epithelia are no longer considered to be the cell of origin for ovarian cancer, changes in PTP1B levels in combination with changes in the levels of other proteins could impact the kinetics of IGF1R activation." (PMID 26861122, 2016).